STAT3 (signal transducer and activator of transcription 3)
Diseases named in the same sentence as STAT3 in open-access papers (continued):
Sharing a sentence is not in itself a finding about the gene and the disease.
pancreatic cancer (continued). "Pancreatic cancer cells were determined to express the transcription factors STAT1, STAT3, and STAT6 at various levels, while Stat3 phosphorylation was enhanced in response to IL-4 stimulation, and STAT6 nuclear translocation was increased after exposure to IL4." (PMID 33804263, 2021). "Recently, an interesting study showed that during early pancreatic cancer development, non-malignant cells secreted IL-6 to activate signal transducer and activator of transcription 3 (STAT3) signaling in hepatocytes." (PMID 34067719, 2021). "Moreover, STAT3 inhibitors, such as the small-molecule inhibitor BBI-608 and monoclonal antibody SBT-100 have obtained orphan drug identification in pancreatic cancer and are undergoing clinical phase ΙΙΙ and Ι study, respectively." (PMID 33420372, 2021). "The use of conditional knockout mice also proved that STAT3 is not dispensable for pancreas development and homeostasis, suggesting its specificity for the pancreatic cancer treatment." (PMID 33420372, 2021). "In addition, blockade of autophagy reduces pancreatic cancer stem cell activity, thereby potentiating the anticancer effects of GEM, with reduced phosphorylation of ERK and STAT3." (PMID 34771150, 2021). "As a paracrine factor, LIF binds to the heterodimer of LIFR and gp130 on the surface of pancreatic cancer cells, activates the JAK/STAT3 pathway and ultimately induces transcription of genes which are known to regulate cell cycle, apoptosis, angiogenesis and invasion." (PMID 33630157, 2021). "To further investigate the significance of the pYs‐related signaling pathways in human pancreatic cancers, we measured the phosphorylation levels of total Tyrosine, EGFR, and STAT3 in PDAC and adjacent tissues in patients who have received surgical resection of their tumors." (PMID 33783993, 2021). "In PSC-conditioned medium-stimulated human pancreatic cancer cells, LIF receptor (LIFR) and its co-receptor IL-6 signal transducer (IL6ST, also known as gp130) are only receptors identified as interacting partners with STAT3 (immunoprecipitation)." (PMID 33572223, 2021). "Mechanistically, upregulated ciRS-7 was found to inhibit the expression of miR-7 and upregulate the expression of epidermal growth factor receptor (EGFR) and signal transducer and activator of transcription 3 (STAT3), to affect the proliferation and invasion of pancreatic cancer cells." (PMID 33710802, 2021). "Furthermore, in epithelial cells, TLR7 stimulation leads to multiple signaling activation, such as STAT3, Notch, MAP kinase and NF-κB in epithelial cells, confirming that pancreatic cancer is driven by stromal inflammation." (PMID 34884547, 2021). "Interfering with gp130 expression effectively inhibited STAT3 phosphorylation in tumor cells exposed to co-cultured CM, and partially impaired the co-cultured CM-induced migration, invasion, and EMT of pancreatic cancer cells." (PMID 32308766, 2020). "Likewise, through STAT-3 dependent up-regulation of MMP9, in vitro IL-22 has been shown to enhance the metastatic potential of pancreatic cancer cell lines." (PMID 33042126, 2020). "In conclusion, we have proven that L-4F could inhibit pancreatic cancer progression, mostly by reducing the infiltration of PMN-MDSCs and weakening their immunosuppressive function by decreasing the phosphorylation of STAT3 in the tumor tissue." (PMID 32425796, 2020). "Recent studies have demonstrated that induced MK is significantly associated with chemoresistance in pancreatic cancer via the activation of NF-κB signaling and Hes1-induced JAK2/STAT3 signaling through cleavage and activation of MK-mediated Notch signaling." (PMID 31952344, 2020). "From this point of view, STAT3 and its effector MYC may be a pancreatic cancer driver in hyperglycemia." (PMID 32609742, 2020).
pancreatic cancer (continued). "Mechanistically, SC‐derived Interleukin 6 (IL6), which was induced by co-culture with pancreatic cancer cells, augmented cancer cell migration and invasion by activating STAT3 signaling in cancer cells, while IL6 neutralization or STAT3 downregulation abrogated these effects." (PMID 32308766, 2020). "Elevated leptin may promote pancreatic tumor invasion and metastasis, activating the Janus kinase 2 (JAK2)/signal transducer and activator of transcription 3 (STAT3) axis." (PMID 33167521, 2020). "For example, STAT-3 activation counteracts the effects of STAT-1 on p21 and p27 expression and activates a survival MAPK and AKT-dependent pathway which inhibits the occurrence of autophagy in pancreatic cancer cells." (PMID 31320837, 2019). "Furthermore, IL-6 showed a stronger ability to activate/phosphorylate STAT3 at Tyr705 than did LIF or another IL-6 family member, IL-11, in human pancreatic cancer cells." (PMID 31296870, 2019). "Then, the pancreatic cancer cells were incubated with various concentrations of IL-6 (0, 0.01, 1, 10 and 100 nM), and the CD59 expression and phosphorylation levels of STAT3 in cancer cells were significantly elevated to levels comparable to those in cells stimulated with THP-1 macrophages." (PMID 31685825, 2019). "In the KrasG12D pancreatic cancer model, strong non-cell-autonomous STAT3 activation in tumor cells was observed." (PMID 31694340, 2019). "In the pancreatic cancer cell lines AsPC-1 and PANC-1, miR-1181 decreases stem markers and pluripotent gene expression, suppresses tumorsphere formation, and shrinks the CSC population by inhibiting SOX2 and STAT3 expression." (PMID 31861404, 2019). "Using this framework, our results novelly showed that compartment-specific STAT3 activities, but not STAT3 mRNA, have prognostications towards clinical values within pancreatic cancer datasets." (PMID 31796877, 2019). "Exosomes shed by pancreatic cancer cells can be internalized by CD14+ monocytes and impart a monocytic MDSC phenotype by downregulating HLA-DR expression and activating signal transducer and activator of transcription 3 (STAT3) signaling, with increased arginase I and ROS production as a result." (PMID 29903049, 2018). "It has been reported in the literature that α-solanine acts as an antitumor agent in inhibition of Wnt/β-catenin, Akt/mTOR, Stat3 and NF-κB pathways in non-toxic concentrations in healthy cells and in pancreatic cancer cells (PANC-1)." (PMID 29799481, 2018). "SCH772984 potentiates the cytotoxic effect of CuB on pancreatic cancer cells through complementary inhibition of EGFR, PI3K/Akt/mTOR, STAT3 and ERK signaling, followed by an increase in the pro-apoptotic protein Bim and a decrease in the anti-apoptotic proteins Mcl-1, Bcl-2, Bcl-xl and survivin." (PMID 29262554, 2017). "Our previous study showed that Raloxifene selectively inhibits STAT3 phosphorylation induced by IL-6 in the GP130/JAK/STAT3 signaling pathway in pancreatic cancer cell-lines (PANC-1) that express GP130, but not ER." (PMID 28430601, 2017). "And another report demonstrated that activated interleukin-6/Stat3 signaling could induce suppressor of cytokine signaling 3 (SOCS3) methylation via DNMT1, resulting in pancreatic cancer growth and metastasis." (PMID 28360411, 2017). "Interestingly, our results showed a decrease in EGFR, STAT3, Akt and S6 activities and an increase in ERK activity in 2 CuB-treated pancreatic cancer cell lines." (PMID 29262554, 2017). "Though gemcitabine is known to induce apoptosis via p38 activation in pancreatic cancer cells, STAT3 phosphorylation status is not altered." (PMID 28418923, 2017). "A recent study suggested RES induced apoptosis and cell cycle arrest via modulation of ERK1/2 and GSK3β pathways in human pancreatic cancer cell line AsPC1 without phosphorylated STAT3 and NFκB50." (PMID 27539371, 2016).
pancreatic cancer (continued). "The protein levels of pSTAT3, but not of total STAT3, increased in a dose-dependent manner in both pancreatic cancer cell lines after 24 hours of gemcitabine treatment." (PMID 27556697, 2016). "In our system, due to the crosstalk between adipocytes and pancreatic cancer cells, we observed an increase in STAT3 phosphorylation in Tyr-705 in cancer cells; as a consequence of IL6/STAT3 signaling pathway activation we observed in MiaPaCa2 cells an increase in WNT5a expression." (PMID 26958939, 2016). "Our results support that Lip-FLLL32 could be a promising therapeutic agent sensitizing pancreatic cancer cells to chemo/radio-therapy via efficient delivery of FLLL32 and then inhibition of STAT3 in vivo." (PMID 26887043, 2016). "Finally, our data suggests that Cav-1 depletion in pancreatic cancer cells affects various pathways, particularly the JAK/STAT pathway, by decreasing activation of JAK2 and STAT3 and by increasing SOCS2, PIAS3, and DUSP5 inhibitory signals." (PMID 26065715, 2015). "Moreover, patient-derived orthotopic xenografts can exhibit tumor angiogenesis, whereas conditioned media (CM) from KRC-derived pancreatic cancer cells (PCCs) enhance endothelial cell (EC) growth and migration, and activate canonical TGF-β signaling and STAT3." (PMID 25762644, 2015). "Moreover, the presence of an autocrine signaling loop between HIF-1a and STAT-3 was demonstrated in pancreatic cancer cell lines, where hypoxia mediates an increase in IL-6 production through HIF-1a leading to activation of STAT-3." (PMID 26517240, 2015). "PKCι promotes the transformed phenotype of pancreatic cancer, at least in part, via activation of Rac1-MEK/ERK signaling, whereas a major mechanism by which PKCζ regulates pancreatic cancer cell transformed growth is via promotion of STAT3 activation." (PMID 25915428, 2015). "STAT3, a member of the signal transduction and activation of transcription (STAT) family, has been frequently overexpressed in a wide variety of human tumors including pancreatic cancer." (PMID 24040078, 2013). "Additionally, Wei and coworkers also reported that STAT3 activation regulates VEGF expression and angiogenesis in human pancreatic cancer cells." (PMID 24199193, 2013). "In EGF-STAT1 and EGF-STAT3, both gene pairs are involved in pancreatic cancer, EGF pathway, and signal transduction pathway; both STAT1 and STAT3 are activated by the Jak kinase in response to EGF, where JAK2/STAT3 signaling is required for EGF-driven ovarian cancer." (PMID 23940583, 2013). "Furthermore, STAT3 shRNA can enhance the inhibitory effects of EGCG on cell motility and viability in pancreatic cancer cells, suggesting that EGCG can influence some other gene/pathway besides STAT3." (PMID 22348037, 2012). "Our results demonstrate that activation of the STAT3 signaling pathway is critical for the growth of pancreatic cancer cells and suggest that EGCG targeting STAT3 signaling may be a potential therapeutic intervention for pancreatic cancer." (PMID 22348037, 2012). "STAT3 shRNA completely inhibited the expression of cyclin D1 in both pancreatic cancer cell lines in the presence or absence of EGCG." (PMID 22348037, 2012). "Co-incubation of pancreatic cancer cells with IFN-β and TGZ suppresses STAT3 activation and delays G0/G1-S phase progression that occurred together with an increase in p21 and p27 protein expression that was more evident after 24 hours of treatment with the pharmacological combination." (PMID 23028383, 2012). "Finally, since cell migration represents an important step in the progression and dissemination of pancreatic cancer, we evaluated the effects of APE1 and STAT3 blockade on the response of PDAC cells to chemotactic stimuli, using the xCELLigence system." (PMID 23094050, 2012). "Additionally, gemcitabine and CP690550 alone inhibited STAT3 target genes and synergized with EGCG to inhibit cell viability and induce apoptosis in pancreatic cancer cells." (PMID 22348037, 2012).
pancreatic cancer (continued). "These current data suggest that STAT3 knockdown significantly altered invasion ability of the pancreatic cancer cells, without any metastatic tumors in the lymph nodes in both experimental and control groups." (PMID 21991388, 2011). "Also, Wei and colleagues reported that STAT3 activation regulates the expression of VEGF and human pancreatic cancer angiogenesis Furthermore, several papers described the role of STAT3 as a potential modulator of HIF-1α-induced VEGF signaling in cancer cells." (PMID 21731766, 2011). "Despite the clear importance of Stat3 in cell proliferation, invasion, metastasis, and survival in human pancreatic cancer, its potential molecular contribution to pancreatic cancer invasion and metastasis has not been fully characterized." (PMID 20482858, 2010). "However, low-dose VPA (0.5 mM), in combination with gemcitabine, promotes the migration and invasion of pancreatic cancer, and high-dose VPA (5 mM) enhances the sensitivity of PCCs to gemcitabine through p38 activation, which suppresses the activation of STAT3 and Bmi1." (PMID 41020871, 2025). "Therefore, our results reveal the role of CTHRC1 in CAFs in pancreatic cancer, and the CTHRC1/LIF/STAT3 signaling axis may be a promising prognostic marker and therapeutic target for patients with pancreatic cancer." (PMID 40751418, 2025). "Subsequent coculture of pancreatic cancer cells with CTHRC1‐knockdown CAFs‐CM and CTHRC1‐reconstituted‐overexpressing CAFs‐CM demonstrated that CAF‐derived CTHRC1 promotes epithelial‐mesenchymal transition and positively regulates STAT3 signaling pathway activation in cancer cells." (PMID 40751418, 2025). "Finally, to further confirm that CTHRC1 in CAFs activates STAT3 signaling in pancreatic cancer cells via LIF regulation, we cocultured CTHRC1‐overexpressing CAFs‐CM with pancreatic cancer cells in the presence of the LIF inhibitor EC330 and STAT3 inhibitor Stattic." (PMID 40751418, 2025). "Furthermore, we used small interfering RNA to silenceIL15 in activated PSCs and detected whether it affects the protein level of pancreatic cancer cells.IL15 silencing decreased IL15RA, p-STAT3, GPX4 and ACSL3 expression levels." (PMID 39396119, 2024). "Additionally, a combinatorial treatment with an antisense STAT3 inhibitor, AZD-1950, and an anti-PD-L1 monoclonal antibody, durvalumab, has advanced to a phase II clinical trial which includes advanced refractory pancreatic cancer patients (NCT02983578), with minimal toxicity being reported." (PMID 39199647, 2024). "Notably, in pancreatic cancer, gemcitabine efficacy necessitates p38-MAPK activation, while gemcitabine resistance is augmented by the activation of STAT5, SRC, and STAT3." (PMID 39000545, 2024). "Therefore, we suspect that in pancreatic cancer, knockout of CD73 may lead to the inhibition of the IL-6/JAK/STAT3 pathway, thus inhibiting tumor cell growth." (PMID 37835536, 2023). "Another STAT3 inhibitor of great importance is XZH-5, which has been demonstrated to inhibit STAT3 phosphorylation (Tyr705), thereby leading to a decreased STAT3 activities, which resulted in inhibited colony formation, cell migration, and apoptosis induction in human pancreatic cancer cells." (PMID 36975494, 2023). "Moreover, the polyadenosine diphosphate ribose polymerase inhibitor pamiparib upregulated programmed death ligand 1 (PD-L1) expression on the surface of pancreatic cancer cells in vitro and in vivo via the JAK2/STAT3 pathway, with a significant increase in CD8+ T cells in TME." (PMID 36291659, 2022). "Recently, a preclinical study evaluated the combined effects of an anti-PD-1 antibody with a STAT3 inhibitor (STX-0119) in an in vivo pancreatic cancer model; however, no significant anti-tumor benefits were observed and the study was terminated due to safety concerns from excessive weight loss." (PMID 35053592, 2022).
pancreatic cancer (continued). "Another study developed a Napabucasin-based STAT3 PROTAC XD2-149, which inhibited STAT3 signaling in pancreatic cancer cell lines, but did not induce proteasome-dependent STAT3 degradation, suggesting that targeting STAT3 degradation remains challenging (Hanafi, Chen, & Neamati, 2021)." (PMID 36034876, 2022). "Some STAT3 inhibitors have not shown a clear advantage in patients with pancreatic cancer." (PMID 36291659, 2022). "Furthermore, based on TCGA data, a negative correlation between Gadd45g and Stat3 expression was found in pancreatic cancer patients (r = −0.197, p = 0.00831)." (PMID 35211358, 2022). "Specifically, the pancreatic cancer stem cell surface marker c-Met reacts to secreted ligands and markers CD44 and CD24 foster intercellular interactions, thereby activating pathways such as Stat3, Notch, and β-catenin in pancreatic cancer stem cells and thus stimulating self-renewal." (PMID 33928036, 2021). "Interestingly, STAT3 activity is inhibited by the knockdown of APE/Ref-1 but does not affect its phosphorylation or nuclear translocation in pancreatic cancer cells." (PMID 33003453, 2020). "Therefore, it is safe to conclude that Cc/Glt NM can induce pancreatic cancer cell apoptosis by increasing ROS production to trigger the downstream signaling of ER stress, namely, Bip/p-PERK/p-elF2a pathway and inhibit the phosphorylation of STAT3." (PMID 32891174, 2020). "It is worth mentioning that the IL-6 produced by non-neoplastic components within pancreatic tumors could activate proinflammatory STAT3 signaling in hepatocytes." (PMID 32724299, 2020). "Finally, a study focusing on pancreatic cancer demonstrated that, L1CAM-ECD cleaved from Schwann cells homotypically interacts with L1CAM on tumor cells leading to the activation of ERK and STAT3-mediated expression of MMP-2 and -9 which facilitates cancerous nerve invasion." (PMID 31455004, 2019). "Second, our STAT3 target profiles are in part based on pancreatic cancer cell lines, which might not fully reflect pancreatic cancer cells within a tumor environment." (PMID 31796877, 2019). "Additionally, the SP STAT3-mediated enhancement of ETC activity, mitochondrial membrane polarization, and ATP production were also shown to be involved in K-RAS-driven myeloid malignancy and in the development of pancreatic cancer." (PMID 30231582, 2018). "This suggests that STAT3 is not a unique therapeutic target in pancreatic cancer cells." (PMID 29262554, 2017). "Moreover, STAT3 activation induced by Pim-3 increases the transcription of Hif-1α, thereby up-regulating the expression of MDR1 (P-glycoprotein) gene, resulting in reduced chemosensitivity in human pancreatic cancer cells." (PMID 29069816, 2017). "Our results indicate that gemcitabine may prevent STAT3 phosphorylation in myeloid cells while we did not see any significant difference in STAT3 phosphorylation upon gemcitabine treatment in pancreatic tumor cell lines." (PMID 27687804, 2016). "Since STAT3 phosphorylation/activation can be induced by MEK inhibitors, we hypothesize that the combined treatment with STAT3 and MEK inhibitors would have enhanced therapeutic effects in K-Ras mutant pancreatic cancer and colon cancer cells compared with MEK or STAT3 inhibitor alone." (PMID 25961376, 2015). "In addition, Trametinib showed increased suppression on tumor growth in vivo in STAT3 knockdown pancreatic cancer cells compared with tumor growth of control cells without STAT3 knockdown." (PMID 25961376, 2015). "Here, we examined the effects of epigallocathechin gallate (EGCG) on STAT3 signaling in pancreatic cancer cells, and assessed the therapeutic potential of EGCG with gemcitabine or JAK3 inhibitor CP690550 (Tasocitinib) for the treatment and/or prevention of pancreatic cancer." (PMID 22348037, 2012).